CREM (cAMP responsive element modulator)
Description:
Transcriptional regulator that binds the cAMP response element (CRE), a sequence present in many viral and cellular promoters. Isoforms are either transcriptional activators or repressors. Plays a role in spermatogenesis and is involved in spermatid maturation. [Isoform 6]: May play a role in the regulation of the circadian clock: acts as a transcriptional repressor of the core circadian component PER1 by directly binding to cAMP response elements in its promoter.
Synonyms: ICER; hCREM-2; CREM-2
Tractability: PROTAC: UniProt records ubiquitination sites on it.
Gene: Protein-coding gene on chromosome 10 (35,126,791 to 35,212,958, forward strand). Ensembl gene ENSG00000095794.
Subcellular location: Nucleus; Cytoplasm (Isoform 6)
Subcellular location (Human Protein Atlas): Nucleoplasm; Vesicles
Pathways (Reactome):
Circadian clock: Phosphorylated BMAL1:CLOCK (ARNTL:CLOCK) activates expression of core clock genes
Gene Ontology:
Molecular function: DNA-binding transcription repressor activity, RNA polymerase II-specific; protein binding; RNA polymerase II transcription regulatory region sequence-specific DNA binding; sequence-specific double-stranded DNA binding; cAMP response element binding protein binding; DNA binding; DNA-binding transcription factor activity, RNA polymerase II-specific; RNA polymerase II cis-regulatory region sequence-specific DNA binding; DNA-binding transcription factor activity
Biological process: negative regulation of transcription by RNA polymerase II; regulation of DNA-templated transcription; cAMP/PKA signal transduction; regulation of transcription by RNA polymerase II; signal transduction
Cellular component: nucleoplasm; ATF4-CREB1 transcription factor complex; chromatin; nucleus; cytoplasm; transcription regulator complex
Genetic constraint (gnomAD): Loss-of-function variants: 11 observed, 34.13 expected, observed/expected ratio (o/e) 0.32, 90% interval 0.2 to 0.53. The upper end of that interval is the gene's LOEUF score, 0.53, which puts it in group 2 of 6, group 1 being the genes least tolerant of losing a copy. Missense variants: 263 observed, 353.3 expected, observed/expected ratio (o/e) 0.74, 90% interval 0.67 to 0.82. Synonymous variants: 115 observed, 118.87 expected, observed/expected ratio (o/e) 0.97, 90% interval 0.83 to 1.13.
Homologues: Orthologues: dog CREM (93% identical), macaque CREM (93% identical), rat Crem (91% identical), chimpanzee CREM (90% identical), mouse Crem (87% identical), guinea pig CREM (76% identical), Caenorhabditis elegans crh-1 (33% identical), zebrafish crema (30% identical), Drosophila melanogaster CrebB (29% identical), tropical clawed frog crem (28% identical), Drosophila melanogaster CrebA (16% identical), Caenorhabditis elegans atf-6 (14% identical), and 2 more. Paralogues in human: CREB1 (63% identical), ATF1 (51% identical), CREB3L2 (19% identical), ATF6 (19% identical), CREB3L3 (18% identical), CREB3L1 (18% identical), ATF6B (17% identical), CREB3L4 (17% identical), CREB3 (14% identical).
Diseases named in the same sentence as CREM in open-access papers:
CREM is named in the same sentence as 95 diseases in open-access papers, as found by Europe PMC text mining. Sharing a sentence is not in itself a finding about the gene and the disease. The quoted sentences say what the papers report.
mesenchymal tumor (9 papers, 2018 to 2025). "Based on these findings, the tumor was diagnosed as an epithelioid mesenchymal tumor with EWSR1::CREM gene fusion." (PMID 40242428, 2025). "CREB family (CREB1, ATF1, and CREM) gene fusions are defining markers in diverse mesenchymal neoplasms (clear cell sarcoma, angiomatoid fibrous histiocytoma, and others)." (PMID 34228212, 2022). "Fusions between the FET gene family (EWSR1 and FUS) and one of the CREB transcription factor family members (ATF, CREB1, and CREM) have been increasingly reported in a variety of mesenchymal neoplasms that are clinically, anatomically, and phenotypically distinct." (PMID 40748380, 2025).
systemic lupus erythematosus (9 papers, 2007 to 2025). An autoimmune multi-organ disease typically associated with vasculopathy and autoantibody production. "Since ICER/CREM deficiency affected Th17 differentiation in vitro and in two different Th17-related disease models, we considered that ICER/CREM deficiency would delay or protect lupus-prone mice form developing disease." (PMID 27680869, 2016). "Collectively, ICER/CREM deficiency rescues multiple lupus characteristics and extends the lifespan of B6.lpr mice." (PMID 27680869, 2016). "CREM is involved in the pathogenesis of systemic lupus erythematosus (SLE), in addition to various immune-mediated validation processes." (PMID 37600067, 2023). "Previous studies have shown that CREM has important roles in normal T-cell physiology and contributes to aberrant T-cell function in patients with systemic lupus erythematosus (SLE)." (PMID 34938728, 2021). "So far CREM has only been discussed in the context of autoimmunity being an important molecule in the T cell pathogenesis of systemic lupus erythematosus." (PMID 26459392, 2015). "Increased CREM expression was found in T cells of patients with another autoimmune disease, systemic lupus erythematosus." (PMID 17509149, 2007). "The balance between CREB and CREM activity, which is important in determining whether IL-2 is upregulated or downregulated, is altered in lupus T cells." (PMID 24864268, 2014). "The high CREM and CREB ratio in lupus T cells contributes to IL-2 deficiency." (PMID 24864268, 2014). "CREMα, a CREM isoform generated by alternative splicing, has key functions as an epigenetic and transcriptional regulator of cytokine expression in T cells from systemic lupus erythematosus (SLE) patients." (PMID 28066428, 2016). "There are at least 2 proposed mechanisms to explain the increased CREM and reduced CREB activities in lupus T cells." (PMID 24864268, 2014). "CREM is a transcription factor cAMP response element modulator and is crucial for the proliferation of double-negative T cells in systemic lupus erythematosus." (PMID 37762493, 2023).
infertile (6 papers, 2016 to 2023). "There are reports that CREM alteration or deficiency affect protamine expression; thereby leading to infertility because of disorder in the round spermatid maturation." (PMID 32960520, 2021). "Overall, the only noticeable difference in basal phenotype between mutants and controls was the infertility of CREM-deficient male mice, a well-known issue due to the crucial role of CREM in spermatogenesis." (PMID 29044198, 2017). "CREM mutation in mice causes the disturbances to the early stages of spermiogenesis, and deletion of CREM gene causes infertility in male mice." (PMID 27733803, 2016). "Studies in infertile populations have revealed the absence or low expression of CREM or its cofactors, contributing to infertility." (PMID 37628737, 2023). "The relative abundance in transcripts of few TH2B associated genes- CREM, CDYL, PRKAG2, CATSPERB, TSGA10 and TSSK1B was studied in sperm of fertile and infertile men with asthenozoospermia-, oligozoospermia- or oligoasthenozoospermia." (PMID 33933143, 2021). "Furthermore, radiation therapy, a known treatment with detrimental effects on the male reproductive system, including permanent infertility, has been shown to decrease CREM expression, decrease testis weight and induce atrophic seminiferous tubules." (PMID 37628737, 2023). "This review examines the importance of CREM as a transcription factor for sperm production and its relevance in male fertility, infertility and the response to environmental xenobiotics that may affect CREMτ expression and the downstream regulation that alters male fertility." (PMID 37628737, 2023).
male infertility (5 papers, 2011 to 2023). The inability of the male to effect fertilization of an ovum after a specified period of unprotected intercourse. "The down-regulation of CREM by various compounds, whether pollutants or medical treatments, can impair spermatogenesis and lead to male infertility." (PMID 37628737, 2023). "It shouldbe noted that both CREB and CREM are known to be the master-switch transcriptionfactors coupled to the FSH-regulated cAMP pathway, mutations of which are knownto be related to male infertility or shown to affect spermatogenesis." (PMID 21625623, 2011). "Therefore, CREM expression could be used as a biomarker to detect and even counteract male infertility." (PMID 37628737, 2023).
melanoma (5 papers, 2013 to 2025). A malignant, usually aggressive tumor composed of atypical, neoplastic melanocytes. "To explore an oncogenic contribution of EWSR1/CREM in melanoma, we again used RNAi to knockdown expression of the fusion." (PMID 23637631, 2013). "We hypothesize that inducible cAMP early repressor (ICER), an antagonist of CREB and CREM in this context, may play a critical role in melanoma resistance and tumor progression." (PMID 40719625, 2025). "Thus, EWSR1/CREM potentially represents the first oncogenic gene fusion discovered to date in melanoma." (PMID 23637631, 2013). "Breakpoint analysis also identified a novel EWSR1/CREM fusion in melanoma (CHL-1)." (PMID 23637631, 2013). "In this study, we performed transcriptional profiling of the melanoma cell line CHL-1, with depletion of endogenous EWSR1::CREM protein using siRNA mediated knockdown." (PMID 36966162, 2023). "To interrogate the effect of CREM knockdown on non-malignant and malignant cells, we used three cell lines: Human embryonic kidney cell line HEK 293, human prostate carcinoma cell line PC-3, and human melanoma WM164 cell line." (PMID 36966162, 2023). "Concordant ChIP-SEQ results coupled with our RNA-seq analysis provides evidence of ICER regulation, and antagonism of CREM/CREB, however, absent melanoma specific ChIP-seq data targeting CREM, it is unclear how cell type specific chromatin accessibility may impact ICER/CREM binding." (PMID 40719625, 2025).
sarcoma (5 papers, 2021 to 2025). A usually aggressive malignant neoplasm of the soft tissue or bone. "The authors have considered the two examples as unclassified EWSR1::CREM fusion sarcomas." (PMID 39249507, 2024).
Anxiety (3 papers, 2005 to 2017). Intense feelings of nervousness, tension, or panic often arise in response to interpersonal stresses. "In another study, the CREB-related transcription factor CREM was shown to be involved in the control of anxiety-like behavior." (PMID 16102169, 2005).
autoimmune disease (3 papers, 2007 to 2023). A disorder resulting from loss of function or tissue destruction of an organ or multiple organs, arising from humoral or cellular immune responses of the individual to their own tissue constituents. "In addition to its role in inflammation and autoimmune diseases, Taiwanese scholars found that CREM expression was increased in patients with rheumatoid arthritis and its variants were involved in the progression of the disease." (PMID 37275908, 2023).
Autoimmunity (3 papers, 2016 to 2025). The occurrence of an immune reaction against the organism's own cells or tissues. "To understand the role of CREM in autoimmunity, we recently generated a mouse with a transgenic overexpression of CREMα selectively in T cells." (PMID 28066428, 2016). "Robust literature supports a role for CREM in SLE and other systemic and organ-specific autoimmune conditions, including psoriasis, rheumatoid arthritis, and oligoarticular juvenile idiopathic arthritis (21, 42, –, 45)." (PMID 40576353, 2025).
gastric adenocarcinoma (3 papers, 2014 to 2023). "In this study, we used the integrated Bioinformatics Methods to explore the role of CREM in gastric adenocarcinoma (GAC)." (PMID 34938728, 2021). "Transcriptional repressor cAMP response element modulator (CREM) is induced by cAMP signaling pathway and positively correlated with exhausted marker genes in gastric adenocarcinoma." (PMID 37180158, 2023).
Hyperglycemia (3 papers, 2012 to 2025). An increased concentration of glucose in the blood. "In non-immune tissue types, diminished CREM expression in visceral adipose tissue was associated with decreased insulin sensitivity in obese humans and mice; and CREM-dependent gene expression regulated the response to hyperglycemia in cardiomyocytes." (PMID 40576353, 2025).
prostate carcinoma (3 papers, 2021 to 2023). A carcinoma that arises from epithelial cells of the prostate gland. "The fusion of FOXP2 and CREM is novel and has not yet been associated with prostate cancer." (PMID 35625354, 2022). "There were no previous descriptions for the fusions NAIP:OCLN, PDE1C:DNAJC6, KANSL1:ARL17B, FOXP2:CREM, and AHSA1:DLG3 in the context of prostate cancer." (PMID 35625354, 2022).
allergic asthma (2 papers, 2015 to 2016). A asthma with a basis in a pathological type I hypersensitivity reaction. "The induction of the Th2 response by PGE2 was found to be mainly cAMP-dependent and recently the transcription factor, cAMP response element modulator (CREM), was characterized as a negative regulator of Th2 responses and a key factor in allergic asthma." (PMID 27375620, 2016). "Thus, we provide evidence that CREM is a negative regulator of the TH2 response and determines the outcome of allergic asthma." (PMID 26459392, 2015).
amebiasis (2 papers, 2018 to 2025). A parasitic infectious disorder caused by amoebas. "CREMa overexpressors displayed enhanced disease activity, suggesting that while protective in amebiasis, the role of CREM in immune activation and chemotaxis may be pathogenic in the context of IBD." (PMID 40576353, 2025). "The role of CREM as a cAMP-mediated transcriptional regulator promises to add to the understanding of intestinal health by delineating a common mechanism of gut inflammation and repair from infectious (amebiasis) and noninfectious (Crohn’s disease and ulcerative colitis) insults." (PMID 30228239, 2018).
colitis (2 papers, 2018 to 2025). Inflammation of the colon. "Further, CREM−/− mice were more susceptible to E. histolytica amebic colitis." (PMID 30228239, 2018). "The additional genetic deletion of CREM reversed the effect of the CREB deletion and resulted in enhanced colitis severity, measured by JLS (The Jackson Laboratory Scoring) score in the transferred mice." (PMID 40777015, 2025).
diabetes (2 papers, 2014 to 2015). "Here, we newly identify cAMP response element modulator [CREM, also known as inducible cAMP early repressor (ICER)] as a signaling player that links the defect in PKA- and CREB-mediated VEGF production to impaired angiogenesis during the course of diabetes." (PMID 25381014, 2015).
glioma (2 papers, 2021 to 2023). A benign or malignant brain and spinal cord tumor that arises from glial cells (astrocytes, oligodendrocytes, ependymal cells). "Single-cell sequencing data showed that CREM is highly expressed in the CD4+ CTLA4 and CD8+ LAYN population in non-small cell lung cancer, and CREM is highly expressed in the CD8+ T-cell exhaustion population in glioma." (PMID 34938728, 2021). "LUAD patients and glioma patients with higher CREM expression had shorter overall survival." (PMID 34938728, 2021). "In addition, we briefly explored the role of CREM in lung cancer and glioma." (PMID 34938728, 2021). "Notably, CREM expression significantly impacts prognosis in gliomas and LUAD." (PMID 34938728, 2021). "Notably, we analyzed the role of CREM in lung cancer and glioma." (PMID 34938728, 2021). "The top five TFs with the highest correlations in both datasets consisted of STAT1, MEOX2, CREM, NR2F2, and IRF3, indicating that they were likely to regulate the expression of SERPINF1 in glioma." (PMID 36980858, 2023). "The results showed that STAT1, CREM, and NR2F2 were the most likely upstream TFs of SERPINF1 in glioma." (PMID 36980858, 2023). "Higher CREM expression predicted poor outcome in patients with GAC, glioma, and LUAD." (PMID 34938728, 2021). "Furthermore, STAT1, CREM, and NR2F2 may participate in the transcriptional regulation of SERPINF1 in glioma." (PMID 36980858, 2023).
inflammatory bowel disease (2 papers, 2018 to 2025). A spectrum of small and large bowel inflammatory diseases of unknown etiology. "Other genetic variants in the CREM locus have been previously associated with inflammatory bowel disease, implying CREM is a key mediator of susceptibility to infectious and non-infectious colitis." (PMID 40576353, 2025). "The most strongly associated single nucleotide polymorphism (SNP) within a gene was in an intron of CREM (rs58468612; Pmeta = 8.94 × 10−8), which has been implicated as a susceptibility locus for inflammatory bowel disease (IBD)." (PMID 30228239, 2018).
airway hyperresponsiveness (1 paper, 2015). "CREM deficiency in murine T cells results in enhanced TH2 effector cytokines in vitro and in vivo and CREM−/− mice demonstrate stronger airway hyperresponsiveness in an OVA-induced asthma model." (PMID 26459392, 2015).
allergic disease (1 paper, 2015). An immune response that occurs following re-exposure to an innocuous antigen, and that requires the presence of existing antibodies against that antigen. "The factors and mechanisms involved in the inhibition of CREM expression in T cells during allergic sensitization will be a further topic of our future investigation since this could have therapeutic implications for allergic diseases." (PMID 26459392, 2015). "We aimed to analyze the role of CREM, a known transcriptional activator of T cells, with regard to TH2 responses and allergic diseases in men and mice." (PMID 26459392, 2015).
amebic colitis (1 paper, 2018). "Consistent with eQTL data, CREM expression was increased in mice during E. histolytica infection, and CREM−/− mice had heightened susceptibility to amebic colitis." (PMID 30228239, 2018). "Functional evidence suggests a role for CREM during early infection with E. histolytica, and CREM knockout mice were more susceptible to amebic colitis." (PMID 30228239, 2018).
Arthritis (1 paper, 2018). Inflammation of a joint. "Finally deficiency of CREM in T cells ameliorated OVA induced arthritis in vivo." (PMID 29925386, 2018). "Nevertheless, we performed a T cell dependent arthritis model in mice to analyze how CREM signaling in T cells influences the fate of an inflammatory arthritis." (PMID 29925386, 2018).
asthenozoospermia (1 paper, 2021). "Relative expression of CREM was found to be significantly lower in men with asthenozoospermia (p = 0.047) while it was comparable in men with oligozoospermia (p = 0.46) and oligoasthenozoospermia (p = 0.85) to that of fertile men." (PMID 33933143, 2021).
asthma (1 paper, 2015). "To address this question we analyzed CREM expression in humans with atopy and CREM function in murine experimental asthma models and furthermore analyzed transcriptions mechanism of CREM in TH2 cell differentiation." (PMID 26459392, 2015). "Apparently, CREM levels are of functional importance, since CREM−/− mice display increased inflammation and disease severity in an experimental asthma model." (PMID 26459392, 2015).
bone metabolism disorders (1 paper, 2023). "Functional state changes of CREM, FOSL2, FOXC2, RUNX2, and CREB3L1 regulons regarding immunity, cell proliferation, and differentiation identified the important cell stages or subtypes that may be predominantly affected by bone metabolism disorders." (PMID 36793138, 2023).
cardioembolic stroke (1 paper, 2024). "The study analyzing high-throughput gene expression in blood samples has shown that the circulating gene expression makers including CREM, PELI1, and ZAK were verified to be up-regulated in cardioembolic stroke." (PMID 38166912, 2024).
chronic hepatitis B (1 paper, 2024). "Together, these data demonstrate that expression of HBV antigens in infected hepatocytes during chronic hepatitis B is associated with the presence of intrahepatic HBV-specific CXCR6+ CD8 T cells with increased expression of CREM and CREM target genes." (PMID 38987588, 2024).